EGFR (epidermal growth factor receptor)
Diseases named in the same sentence as EGFR in open-access papers (continued):
Sharing a sentence is not in itself a finding about the gene and the disease.
lung cancer (continued). "Unlike other cancer types, such as nonsmall cell lung cancer (NSCLC) that express oncogenic EGFR mutants, EGFR in TNBC is rarely mutated, but it is frequently overexpressed." (PMID 32784650, 2020). "To test whether EZH2 affects the sensitivity of LUAD cells to EGFR-TKIs, we knocked down EZH2 expression in lung cancer cells using siRNA and subjected the cells to the CCK8 assay after exposure to different concentrations of gefitinib for 24–48 h." (PMID 33276757, 2020). "In addition, this study provides conceptual support for the expansion of existing EGFR-TKI by demonstrating that the combination of EGFR-TKI and FGFR-TKI is effective against lung cancer cell lines." (PMID 33092268, 2020). "In lung cancer cells, a signaling network exists between the same RTK family: EGFR, MET, and ERBB3." (PMID 32070026, 2020). "Of note, MB was not toxic to EGFR mutant lung cancer cells at concentrations reached at serum level and shows limited toxicity to these cells at super‐physiological concentrations." (PMID 32391629, 2020). "Also, our results revealed that coadministration of As2O3 and EGFR TKIs sensitized drug effects of lung cancer cells regardless of EGFR mutation status, which may expand the beneficial application of EGFR TKIs in lung cancer patients with amplified wild-type EGFR." (PMID 33042262, 2020). "The trend of EGFR expression following treatment in lung cancer has been sparsely evaluated primarily because most studies were conducted in tumor tissue, hence repeat testing of EGFR expression was not feasible." (PMID 33247670, 2020). "Although EGFR inhibitors are highly efficacious in treating lung cancer, not all lung adenocarcinomas respond to this therapy." (PMID 32781755, 2020). "Similarly, ruxolitinib (another JAK1/2-TKI) had a promising preclinical profile by potently blocking tumor growth in EGFR- and K-RAS-driven lung cancer models and restoring cisplatin-sensitivity to resistant NSCLC cell lines." (PMID 32365499, 2020). "Lin and colleagues identified that both wild-type and catalytically inactive METTL3 can boost the translation of some particular mRNAs such as epidermal growth factor receptor (EGFR) and the Hippo pathway effector TAZ, thus promoting the development of lung cancer." (PMID 32760220, 2020). "In addition, TLR4 signaling promotes proliferation of A549 lung cancer cells through PTGS2/COX-2 (prostaglandin-endoperoxide synthase 2 (prostaglandin G/H synthase and cyclooxygenase)) and epidermal growth factor receptor (EGFR) activation." (PMID 32384667, 2020). "Patients with non-EGFR-T790M tumors tend to develop new metastasis after EGFR-TKI treatment, implying the presence of differential oncogenic properties in EGFR-TKI-resistant lung cancer cells." (PMID 32034239, 2020). "Therefore, we believe that the combined detection of EZH2 with EGFR, KRAS, and BRAF has more advantages in the diagnosis and treatment of lung cancer." (PMID 33299862, 2020).
lung cancer (continued). "In regard to the relationship between the status of EGFR and ALK (EGFR mutations, ALK fusions and EGFR/ALK co-alterations) and the clinical pathological features of patients with lung cancer, there are not many studies conducted." (PMID 33520689, 2020). "MiR-520b-3p could target epidermal growth factor receptor (EGFR), histone deacetylase 4 (HDAC4) and calpain small subunit 1 (CAPN4) respectively to exert tumor-suppressive effects in gastric cancer, lung cancer, prostate cancer." (PMID 32497020, 2020). "HB-EGF is upregulated in many cancers, including lung cancer; and increasingly, studies have confirmed that, in tumors, HB-EGF acts through binding and overactivating the EGFR pathway, generating signals for proliferation, differentiation, migration, and cell survival." (PMID 32695675, 2020). "According to our results, the correlation between the expression of EZH2 and the expression of EGFR in lung carcinoma is not statistically significant." (PMID 33299862, 2020). "Following the advent and clinical adoption of EGFR-targeted therapy in EGFR-mutant NSCLC, a growing list of additional genomically matched targeted therapies continue to emerge in the treatment of various solid cancers including lung cancer." (PMID 31815659, 2019). "Furthermore, Survivin/BIRC5 interacted closely with molecules which were shown to regulate stem cell properties in lung adenocarcinomas (SPC25), influence radiosensitivity in lung cancer (AURKA), or mediate anti-EGFR therapy in NSCLC (AURKB)." (PMID 32039023, 2019). "Portraying the spectrum of tumor recurrence mutations in the same patient without the oncogenic lung cancer driver mutations such as EGFR, KRAS, and EML4‐ALK is an integrative step of understanding lung cancer tumor progression." (PMID 30941903, 2019). "Yet, unlike in colorectal cancer, the number of EGFR copies has no clinical or therapeutic consequence on the management of lung cancer." (PMID 30612556, 2019). "Our data show that the dual PI3K/mTOR inhibitor, BEZ235, is an effective antitumor agent for treating lung cancer in vitro and in vivo, regardless of EGFR status." (PMID 31262325, 2019). "Based on previous findings linking DUOX1 with redox-dependent EGFR activation, the present studies were designed to evaluate whether DUOX1 silencing in lung cancers may be responsible for altered EGFR regulation." (PMID 30890751, 2019). "Furthermore, aberrant expression of BCL2L1 significantly altered the expression of lung cancer biomarkers such as MYC, EGFR, and Vimentin." (PMID 31508368, 2019). "Mutant EGFR, Kras, and EML4-ALK are critical driver oncogenes in lung cancers." (PMID 30971692, 2019). "In lung cancer, cells which have high levels of the pro-apoptotic member BIM (protein and mRNA expression) or those with a low ratio of anti- to pro-apoptotic members following EGFR inhibitor treatment, were more sensitive to the agent." (PMID 31150457, 2019). "We found that BEZ235 suppressed cancer cell proliferation and the growth of lung cancer tumors regardless of their EGFR status by downregulating cyclin D members through both transcriptional inhibition and proteasome-mediated degradation." (PMID 31262325, 2019). "Interplay has been reported between EGFR, STAT3, and ALK in lung cancers." (PMID 30634502, 2019). "Besides serine phosphorylation, tyrosine phosphorylation of GLK is induced by EGF stimulation in A549 lung cancer cell lines, suggesting that EGF receptor (EGFR) signaling regulates GLK function or activity." (PMID 31640697, 2019). "However, very few studies have examined the connection between EGFR-TKI resistance and PD-L1 expression in lung cancer." (PMID 31747941, 2019). "Interestingly, in animal and cell models for NTS-expressing lung cancers, treatment with an NTSR1 antagonists resulted in increased cytotoxicity of anti-EGFR chemotherapy." (PMID 31489118, 2019).
lung cancer (continued). "The ability of first generation TKIs, gefitinib and erlotinib, to effectively inhibit EGFR’s kinase activity were assessed in different wt-EGFR-positive cancer cells: prostate cancer cells PC3 and Du145, lung cancer cell A549, and breast cancer cell MDA-MB-231." (PMID 31121829, 2019). "At present, the therapeutic relevance of EGFR endocytosis with regard to drug resistance in lung cancer has not been clarified." (PMID 35582586, 2019). "They furthermore portray a CET resistance landscape resembling that of EGFR inhibitors in lung cancer or BRAF inhibitors in melanoma where non-genetic resistance can occur." (PMID 31287991, 2019). "AXL hyperactivation and evidence for EMT were previously reported in multiple in vitro and in vivo EGFR-mutant lung cancer models with acquired resistance to erlotinib independent of the EGFR T790M alteration and MET activation." (PMID 31815659, 2019). "Also, the toxicity profile of anti-EGFR therapies differs from that of anti-VEGFR therapies, making the combination strategy possible to be tolerated by lung cancer patients." (PMID 31699150, 2019). "In lung cancer, MEK inhibition was correlated with the activation of EGFR and stimulation of its specific RTK (receptor tyrosine kinases) receptor that has the further capacity to induce a transient inhibition of ERK phosphorylation in BRAF non-V600E, but not BRAF V600E, mutant cells." (PMID 31652660, 2019). "Furthermore, delphinidin was demonstrated to have an inhibitory effect of EGFR and VEGFR2 in lung cancer cells." (PMID 31480720, 2019). "We found that IGFBP7 expression was significantly elevated in EGFR-TKI-resistant cells, and that high plasma IGFBP7 levels or IGFBP7 IHC-positive tumors in patients with lung cancer were correlated with shorter PFS when EGFR-TKI was used as the first-line treatment." (PMID 30609749, 2019). "SPRY4 inhibited EGFR expression in NSCLC, a critical factor in lung cancer-targeted therapy." (PMID 30390072, 2019). "Another experiment showed that stromal fibroblast could induce resistance to epidermal growth factor receptor (EGFR) tyrosine kinase inhibitors via hepatocyte growth factor (HGF) mediated crosstalk between tumor cells and stromal cells in lung cancer." (PMID 30680600, 2019). "In conclusion, our study highlighted that lung cancer patients with COPD had a poorer survival outcome than those without COPD when treated with EGFR-TKI." (PMID 31336878, 2019). "In melanoma, colorectal, and lung cancer, BRAF p.V600E is a well-known druggable (anti-EGFR therapy) hotspot affecting the kinase domain of the protein, recently classified as a class I mutant, with the strongest kinase activity, constitutive MAPK cascade, and RAS-independent." (PMID 31197119, 2019). "The difference of recurrence of EGFR/ERBB2/MET is probably due to the different stage of tissues, as the majority data of MSKCC-IMPACT is from late-stage biopsy tissues; while TCGA NSCLC cohort, from early-stage lung cancer primary tumor tissues." (PMID 31739500, 2019). "Epidermal growth factor receptor (EGFR) and MAPK activation-mediated silencing of TET1 was observed in cellular and animal models of lung cancer, but the validity of such a mechanism in human lung cancers is uncertain." (PMID 31842975, 2019). "Next, we tested four lung cancer tissue specimens harboring ALK fusion, EGFR mutation, KRAS mutation, or none." (PMID 30943926, 2019). "Finally, our in vitro results indicate that among the BTK inhibitors RN486 is more powerful than Ibrutinib and AVL-292 in blocking lung cancer cell proliferation and sensitizing drug-resistant NSCLC cells to either EGFR-TKIs and SOC therapy." (PMID 31200752, 2019). "We found that A939572 could significantly impair the phosphorylation of EGFR/PI3K/Akt signaling, and parallelly suppressed the cell vitality, apoptosis in vitro and tumor growth in vivo of lung cancer cells to restore the sensitivity to Gefitinib." (PMID 31019378, 2019).
lung cancer (continued). "A number of studies have documented curcumin mediated anti-proliferative effect in lung cancer cells via modulation of various molecular targets such as STAT-3, EGFR, Forkhead Box O3 (FOXO3a), Eukaryotic Initiation Factors (eIFs), and Transforming Growth Factor-Beta (TGF-β)." (PMID 31817718, 2019). "Preclinical studies targeting the anti-phagocytic CD47 molecule showed promising results in different cancer types including lung cancer, but no data are available on its role in patients acquiring resistance to EGFR TKI treatment." (PMID 32082304, 2019). "c-Met can form heterodimers with EGFR, HER2, and HER3 in lung cancer cells." (PMID 30781364, 2019). "According to TCGA database, among 1940 lung carcinoma patients (including 44 EGFR mutant patients), 106 patients showed NRF2 mutation yet none of these patients co-occurred with EGFR mutation." (PMID 31221965, 2019). "Our primary aim was to assess the lung cancer initiation potency of DEN in FVB/N strain and also determine the KRAS and EGFR status of the tumors which could later serve as a new model for NSCLC research." (PMID 29415661, 2018). "Phase III trials assessing pembrolizumab, nivolumab, or atezolizumab compared to docetaxel as subsequent therapy for patients with metastatic NSCLC found there were no survival benefits for EGFR-mutant lung cancer patients." (PMID 29455650, 2018). "Of course, we did not exclude that the same signaling pathway present in other malignancies, because combined inhibition of EGFR and PI3K/Akt pathways could produce synergistic anti-tumor effects in lung cancers." (PMID 30445978, 2018). "Simultaneous blockade of the two approaches with EGFR-TKI and HGF-MET antagonists could resist the drug resistance and accelerate the successful treatment for lung cancer patients to the full extent." (PMID 29455669, 2018). "Efficacy is seen in pancreatic, colorectal, and lung cancer models regardless of their Kras mutation and TKI resistant EGFR mutation status." (PMID 30323890, 2018). "Similarly, in KRAS-mutant lung cancers, PFS (5.0 months, 95% CI 3.67–6.33) was inferior compared with EGFR-mutant (6.5 months, p = 0.242) and ALK/ROS1-rearranged (9.2 months, p = 0.007) lung cancers." (PMID 29587667, 2018). "show that in EGFR-mutant-driven lung cancer, disruption of the interaction of PI 3-kinase with normal RAS proteins blocks tumor initiation and promotes regression of existing tumors, highlighting an unexpected vulnerability of EGFR-driven lung cancer." (PMID 30590030, 2018). "For instance, a lung cancer patient with no ALK or ROS translocations and EGFR mutations and with a relatively low expression of PD-L1 and a medium to high neoantigen load would be eligible for the adjuvant NCV approach." (PMID 29678194, 2018). "Erlotinib is an effective human epidermal growth factor receptor-tyrosine kinase inhibitor (EGFR-TKI), which was approved for the treatment of advanced pancreatic cancer in combination with gemcitabine as well as for other malignant tumors such as lung cancer." (PMID 29719624, 2018). "Our analysis indicated that for a substantial fraction of lung cancer patients, EGFR testing was not performed immediately after diagnosis." (PMID 29554880, 2018). "The role of MET amplification in lung cancer, particularly in relation to checkpoint inhibition and EGFR WT, has not been fully explored." (PMID 29568386, 2018). "Similar findings have been reported in a study of 47 patients with EGFR-negative lung cancer, in which 13 patients with polysomy 7 showed improved progression-free survival." (PMID 29560123, 2018). "HIV-infected T-cell exosomes quickly enter recipient cells via epidermal growth factor receptor (EGFR) and subsequently stimulate ERK1/2 (extracellular signal-regulated kinase 1 and 2) phosphorylation in HNSCC and lung cancer cells in an EGFR/Toll-like receptor 3 (TLR3)-dependent manner." (PMID 30389917, 2018).
lung cancer (continued). "In the current study, we reveal that CPNE1 repression by miR-335-5p inhibits cell growth and metastasis in NSCLC cells via modulation of the EGFR signaling pathway, and establish the mechanistic interaction between CPNE1 and miR-335-5p in regulation of the lung cancer cell phenotype." (PMID 29970127, 2018). "The exosomes secreted by lung cancer cells, which enrich various proteins, such as EGFR, KRAS, claudins and RAB-family proteins, and promote the development of lung cancer, are effective biomarkers for early diagnosis of lung cancer and the basis of targeted therapy." (PMID 30217217, 2018). "Here, we found that EHD1 is an important factor in EGFR-TKI resistance and the cancer stem-like cell phenotype of lung cancer, which suggests that targeting the NF-κB/miR-590/EHD1 pathway offers potential therapeutic promise for NSCLC patients with EGFR-mutations and acquired EGFR-TKI resistance." (PMID 29549343, 2018). "Previous studies suggested that selective Notch3 inhibition (rather than pan-Notch inhibition) combined with EGFR TKI therapy should be explored as a novel strategy in the treatment of lung cancer patients." (PMID 29795369, 2018). "Molecular targeted therapies such as tyrosine kinase inhibitors (TKIs) in epidermal growth factor receptor (EGFR) mutants and anaplastic lymphoma kinase (ALK) inhibitors in ALK rearranged NSCLC patients have recently advanced the management of lung cancer for a limited proportion of patients." (PMID 30155443, 2018). "However, most patients with NSCLC show acquired resistance to EGFR‐TKIs, and low expression of NF1 is a mechanism of EGFR‐TKI resistance in lung cancer." (PMID 29493886, 2018). "Also, several RTKs including EGFR or their downstream transducers/effectors like Src/Ras/Raf/MEK and PI3K/AKT/mTOR are hyperactivated and contribute to bad prognosis in lung cancer." (PMID 29734788, 2018). "Indeed, EGFR itself is the target of several therapeutics: either RTK inhibitors such as gefitinib, used in lung cancer, or monoclonal antibody inhibitors such as cetuximab, employed against colon cancer." (PMID 30158935, 2018). "Although in vivo experiments are needed to confirm the effects of miR-3140 on EGFR-TKI-resistant cells, our results suggest that miR-3140 may overcome the acquired resistance to EGFR-TKIs in lung cancer." (PMID 29540837, 2018). "Since the clinical correlation of differentially located EGFR proteins in lung cancer has not been completely evaluated; therefore, we intended to investigate the relevance of differentially located EGFR expression in lung adenocarcinoma." (PMID 29950164, 2018). "This review summarizes the hot topics of immunohistochemistry in lung cancer, including (i) adenocarcinoma vs squamous cell carcinoma; (ii) neuroendocrine markers; (iii) ALK, ROS1, and EGFR; (iv) PD-L1 (CD274); (v) lung carcinoma vs malignant mesothelioma; and (vi) NUT carcinoma." (PMID 29538329, 2018). "The NEDD4-mediated EGFR migration signaling is not dependent on the PTEN/PI3K/AKT pathway in lung cancer cells." (PMID 29455656, 2018). "In conclusion, for patients with peripheral lung cancer, R-EBUS-guided bronchial brushing could provide an additional sampling method for diagnosis and EGFR genotyping." (PMID 29643378, 2018). "Although paraneoplastic thrombocytosis is reported to be poor prognostic factor in many types of cancer including lung cancer, platelet count was not prognostic in EGFR-mutant lung adenocarcinoma treated with EGFR-TKI." (PMID 30192878, 2018). "To determine whether the induction of Notch3 and β-catenin signaling is observed in human EGFR mutant NSCLC, we evaluated Notch3 and β-catenin levels in human lung cancer biopsies before and after erlotinib therapy." (PMID 30097569, 2018).